BRAF (B-Raf proto-oncogene, serine/threonine kinase)
Diseases named in the same sentence as BRAF in open-access papers (continued):
Sharing a sentence is not in itself a finding about the gene and the disease.
tumor (continued). "Even within pLGGs, there appears to be a preference for BRAFV600E in supratentorial neoplasms, while cerebellar tumors are dominated by BRAF fusions." (PMID 38789691, 2024). "In line with the findings of large clinical trials and PDO screens, PDOs from patients with a left-sided colon RAS/BRAF-wildtype tumour were most sensitive to panitumumab in our cohort." (PMID 38414064, 2024). "Key to this is the understanding of tumour molecular biology and clinically relevant mutations, such as KRAS, BRAF, and microsatellite instability (MSI), which can predict poorer overall outcomes and a poorer response to systemic therapy." (PMID 39001441, 2024). "BRAF V600E mutation is also extremely rare in TNBC,43,44 and in our cohort was only identified in a single tumor by VE1 IHC." (PMID 37306115, 2024). "In contrast, in CP10 (PCP), consisting of type 2 tumor cells, DKK3 staining was weaker than that in CP1, and S100A8, a type 2 tumor cell marker, was observed around the BRAF V600E-stained area." (PMID 39483146, 2024). "In the future, it is expected that combined immuno- and endoradiotherapies will gain significance in personalized medicine, especially for established tumor mutations like BRCA, RET, and BRAF." (PMID 38256909, 2024). "Detailed results of the molecular BRAF analyses of this cohort have previously been published in a comprehensive analysis of the tumor growth velocity of the reported cohort." (PMID 38580878, 2024). "NCCN guidelines recommend the evaluation of tumor gene status, including KRAS/NRAS and BRAF mutations, as well as HER2 amplification and microsatellite instability (MSI)/mismatch repair (MMR) status, for the systemic treatment of advanced or mCRC45." (PMID 38172565, 2024). "Circulating tumor DNA (ctDNA) can reveal mutations in genes such as KRAS, NRAS, and BRAF and help tailor personalized treatment strategies." (PMID 38790167, 2024). "The opposing relationships of BRAF and KRAS mutations with tumour infiltration of cytotoxic T cells was validated in an independent cohort of 608 CRC patients." (PMID 38040818, 2024). "Transition to an immune-suppressed state is another correlate of BRAF inhibitor resistance and tumor dedifferentiation, suggesting a possible role for concurrent targeted therapy with immunotherapy." (PMID 38275291, 2024). "Expectedly, our data showed that Sorafenib or Lenvatinib treatment effectively improved the anti-tumor efficacy of BRAF inhibitor PLX4720, and relieved the feedback activation of PLX4720-mediated RTKs and their downstream effectors ERK and AKT cascades." (PMID 38795180, 2024). "It is therefore presumed that maintaining ERK activation within a narrow threshold range to avoid engaging tumor suppression is pivotal for mutant BRAF to exhibit the strongest transforming activity." (PMID 36778401, 2024). "It appears to correlate with inferior survival, tumour poor differentiation, proximal location, MSI, CpG island methylator phenotype and BRAF pathogenic variants, notably the p.V600E variant." (PMID 38439814, 2024). "BRAF gain and high-level amplification copy numbers were significantly associated with higher NPI scores and larger tumor sizes compared to neutral copy number status." (PMID 38919805, 2024). "With the growing prominence of targeted therapy in the treatment of advanced or metastatic CRC, the NCCN Panel recommends the determination of tumor gene status for KRAS/NRAS and BRAF mutations." (PMID 39519088, 2024). "The presence of BRAF mutations in certain PTC subtypes results in especially aggressive phenotypes and has been linked to distant metastasis, recurrence, and advanced tumor stage." (PMID 39036614, 2024). "Initiation of the serrated neoplasia pathway typically involves genetic mutations in the BRAF or KRAS genes, followed by tumor suppressor gene methylation known as CpG island methylator phenotype (CIMP)." (PMID 39113889, 2024).
tumor (continued). "In the present study, we described the frequency and spectrum of BRAF alterations in non-CRC GI malignancies by using a large database of patients who underwent tumor somatic profiling and compared it to the frequency of BRAF alteration in CRC." (PMID 38791902, 2024). "Nationwide laboratory diagnostic data incorporated somatic (tumour) testing for dMMR (via immunohistochemistry or microsatellite instability), somatic testing for MLH1 promoter methylation and BRAF status, and constitutional (germline) testing of MMR genes." (PMID 38355963, 2024). "In turn, the double mutant tumors exhibited decreased response to BRAF inhibitors and more prompt resumption of tumor growth after cessation of therapy compared to single mutant mice." (PMID 38275291, 2024). "Because no drugs had been approved for ECD in Japan, we obtained informed consent from the patient and approval from our institutional tumor board and the administration board for using BRAF and MEK inhibitors." (PMID 39724464, 2024). "For example, KRAS and PIK3CA mutations exist within the same tumor; conversely, KRAS and BRAF mutations are mutually exclusive." (PMID 39056802, 2024). "BRAF inhibitors have demonstrated considerable effectiveness in lowering tumor size and slowing disease progression in BRAF-mutant thyroid malignancies." (PMID 38501105, 2024). "Previous studies have established that a subset of BRAF V600-bearing tumor samples contain additional oncogenic or likely oncogenic variants in other genes." (PMID 38790156, 2024). "One approach aiming to prolong duration of response in initially inoperable tumors, has been to administer initially BRAF-directed therapy in order to make the tumor operable and then proceed to surgery." (PMID 39458070, 2024). "For instance, while 85 independent transposon-mutagenized xenograft tumors were analyzed from the in vivo BRAFi resistance screen, 386 independent insertion sites were detected in these tumors within the BRAF locus (>5 sites per tumor on average)." (PMID 38213996, 2024). "The most common off-target bypass signalling, detected in sotorasib and adagrasib resistant tumours, includes MET amplification, BRAF, NRAS, MAP2K1 mutations and RET, ALK, BRAF, FGFR and RAF1 fusions." (PMID 38347643, 2024). "We obtained approval from our institutional tumor board and the administration board for using BRAF and MEK inhibitors." (PMID 39724464, 2024). "Patients with BRAF V600E‐mutated GBM benefit from BRAF/MEK‐inhibition, whereas targeting EGFR alterations was unsuccessful due to poor tumor penetration, tumor cell heterogeneity, and pathway redundancies." (PMID 38899374, 2024). "A total of 34 BRAF-independent mutations were identified in single CTCs [VAF range, 10–100%], while the number of BRAF-independent mutations was lower in tumour biopsies (5 mutations) and cfDNA (11 mutations) bulk samples." (PMID 38177660, 2024). "Accordingly, higher EREG and AREG expression are associated with low CpG island methylator phenotype (CIMP) status as well as WT KRAS/BRAF, left-primary tumor location (PTL), and microsatellite stability (MSS) versus microsatellite instability (MSI)." (PMID 40727266, 2024). "More molecular targets such as anaplastic lymphoma kinase (ALK), ROS proto‐oncogene 1, receptor tyrosine kinase (ROS1), and v-raf murine sarcoma viral oncogene homolog B1 (BRAF) have shown promising anti-tumor efficacy." (PMID 38164287, 2024). "These inhibitors, which directly block the aberrantly active BRAF protein, have showed promise in limiting tumor development." (PMID 38501105, 2024). "Next-generation sequencing showed a low tumor mutation burden (TMB), as well as the BRAF V600E mutation." (PMID 38217014, 2024). "BRAF V600E and NRAS mutations (NRAS Q61R, NRAS Q61K) were found in tumor tissue in 35.5% (11/31) and 19.4% (6/31) patients, respectively." (PMID 38898234, 2024).
tumor (continued). "Bispecific antibodies (BiTEs), which connect T cells to tumor cells by targeting CD3 on T cells and TAAs like EpCAM or CEA, have shown efficacy against KRAS- and BRAF-mutated CRC cells, where conventional therapies fail." (PMID 39684219, 2024). "A case report with a patient with BRAF-mutant advanced PDAC reported objective tumor response to combined vemurafenib plus trametinib treatment." (PMID 38338909, 2024). "Data on targeted therapies for these tumor types is limited, and this report presents BRAF-targeted therapy as a therapeutic option for metastatic pancNET G3." (PMID 38814411, 2024). "First, it is based on a large dataset for a BRAF-V600E-mutation-driven subset of CRC, from a phase 3 clinical trial with integrated tumor and ctDNA analyses via full WES/WTS sequencing and ctDNA genomic profiling." (PMID 39313594, 2024). "The patient's tumor developed resistance to BRAF/MEK/EGFR inhibition with MET amplification, but remained sensitive to FOLFIRI, suggesting MET amplification did not induce resistance to irinotecan." (PMID 39626159, 2024). "LCH is a clonal neoplasm driven by MAPK activation, for which the most common mechanism is BRAF mutation." (PMID 38804700, 2024). "BRAF mutations, especially those that activate the MAPK pathway, can increase tumor immunogenicity and enhance T-cell infiltration, potentially sensitizing tumors to ICIs." (PMID 39796090, 2024). "Several tumors harboring genomic alterations with US Food and Drug Administration-approved indications in other tumor types were found including NF1, PIK3CA, EGFR Exon 19/20 insertions, and BRAF V600E mutations." (PMID 39191445, 2024). "A combination therapy is particularly interesting because the activation of the PI3K/ AKT signaling pathway by BRAFis can lead to the survival of subpopulations of BRAF-inhibited tumor cells." (PMID 39519404, 2024). "The AF of BRAF V600E mutation is suspected to be associated with metastasis in PTC, leading to higher tumor staging and poor outcome." (PMID 38607456, 2024). "Programmed death ligand 1 (PD-L1) expression and tumor mutation burden (TMB) are potentially important indicators of immunotherapy response and are frequently elevated in BRAF-mutant NSCLC24." (PMID 38627602, 2024). "In the animal study, it is further demonstrated that inhibition of SPHK1 by PF-543 (a SPHK1 inhibitor) and/or inhibition of ATF4 by vemurafenib (a BRAF inhibitor to reduce ATF4 production) can inhibit the growth of TMZ-resistant GBM tumor." (PMID 39090107, 2024). "The basis of successfully targeted treatment is, therefore, the inhibition of BRAF kinase to slow or stop the growth of tumor cells." (PMID 38674026, 2024). "Current guidelines stratify the patient groups at risk for PTC based on parameters that predict the recurrence of tumors, such as tumor size, ETE, LNM, and BRAF/TERT mutations." (PMID 38337788, 2024). "By contrast, the tumor organoids did show sensitivity to the combination of erlotinib and vemurafenib even at lower concentrations of the BRAF inhibitor." (PMID 39626159, 2024). "As part of the trial, the mutation status of KRAS (exon 2, 3, and 4), NRAS (exon 2 and 3), and BRAF (codon 600) was previously assessed in tumor tissue." (PMID 39433569, 2024). "Overall, across multiple tumor types, Class 2 and 3 BRAF mutant tumors were enriched for alterations in genes involved in ultraviolet (UV) response and Wnt-beta Catenin signaling." (PMID 38275886, 2024). "Recent clinical trials have reported that metastatic CRC with tumor-promoting mutations in KRAS, PI3KCA, and BRAF is resistant to anti-EGFR therapy." (PMID 38542151, 2024).
tumor (continued). "Studies in mouse models and humans have shown that the presence of BRAF mutations results in lower Nis levels and, consequently a higher rate of RAI-refractory tumours." (PMID 37985676, 2024). "Independent determinants of tumor response to BRAF + MEK inhibitor therapy were evaluated using a multivariate logistic regression model." (PMID 39272837, 2024). "Our study analyzed 83 CRC patient tumor tissues from the National Cancer Institute (NCI) database, examining microsatellite instability (MSI), BRAF, KRAS/NRAS mutations, and neoplastic cell percentage." (PMID 38539463, 2024). "One mechanism of resistance is the transition to an alternative cell state driven by selective pressures from BRAF blockade, which on rare occasion can result in tumor dedifferentiation." (PMID 38275291, 2024). "When a BRAF gene mutation occurs, such as the BRAF V600E mutation, it can lead to sustained aberrant activation of the MAPK signaling pathway, promoting tumor cell proliferation and survival while also affecting cellular autophagy and apoptosis." (PMID 39529955, 2024). "Chemotherapy regimens containing oxaliplatin or irinotecan, along with anti-EGFR for tumors with wild-type RAS/BRAF or anti-VEGF for tumors with RAS/BRAF mutations, were successful in enhancing the rate of tumor removal and improving overall survival." (PMID 38834909, 2024). "BRAF gene expression correlated positively with the tumor size and the NPI scores (r = 0.092 and r = 0.112 (p < 0.001), respectively)." (PMID 38919805, 2024). "Tumor agnostic therapy by use of BRAF inhibitors is yet to be studied but has a potential for opening a new horizon for therapy for patients with advanced disease." (PMID 38449999, 2024). "These drugs target the mutated BRAF protein, effectively disrupting the MAPK/ERK signaling pathway essential for tumor growth." (PMID 38474231, 2024). "The MSI class 1 tumours more often had ARID2 mutations, while class 2 had more BRAF and SMAD4 CNVs, FOXP2 amplifications and 7q11 gains." (PMID 39112715, 2024). "His case was discussed at the North-West London, Genomic Tumour Advisor Board (GTAB) meeting (molecular tumour board [MTB]), with the aim of determining the origin of the somatic BRAF mutation detected and recommendations of further investigations." (PMID 39516362, 2024). "For example, subclones with mutations in genes that confer resistance to targeted therapies, such as BRAF inhibitors, can emerge and lead to tumor recurrence." (PMID 39200315, 2024). "The discovery of BRAF translocation in this tumor contributes to the promise of the clinical implication of selecting new therapeutic options for the treatment of progressive diseases that are refractory to conventional chemotherapy." (PMID 38344591, 2024). "Our findings reveal that BRAF-inhibitor therapy increased tumor immunogenicity, reflected by an upregulation of genes associated with immune activation." (PMID 38631706, 2024). "Tumors with BRAF mutation were treated with dabrafenib and trametinib was added after tumor progression, while tumors with BRAF fusion, NF1 or DLGNT were treated with trametinib." (PMID 39399174, 2024). "The integrated tumor and plasma molecular profiling analyses performed in this study provide comprehensive data from the largest randomized study in BRAF-V600E-mutant CRC." (PMID 39313594, 2024). "On the other hand, the combination of BRAF and tyrosine kinase (TK) inhibitors has been demonstrated to be highly effective in inhibiting tumor development and is an approach for overcoming resistance in clinical trials." (PMID 39281035, 2024). "In the BRAF and RNF43 tumours, co-occurring mutations were observed in ACVR2A (FDR-adjusted P = 0.06) in HM tumours, and AKT1 (FDR-adjusted P = 0.03) and TYRO3 (FDR-adjusted P = 0.08) in the nHM tumours." (PMID 39112715, 2024).
tumor (continued). "Mutations in the genes encoding the components of the MAPK pathway, such as KRAS, NRAS, and BRAF, are frequently observed in LGSOCs, driving uncontrolled cell proliferation and tumor development." (PMID 39409889, 2024). "Another combination regimen, using encorafenib, cetuximab, and an ERK1/2 selective inhibitor, ulixertinib, led to significant tumor regression in the BRAF V600E-mutant CRC model in preclinical studies." (PMID 39684219, 2024). "We assessed the tumor tissue-informed mutation status in the pre-treatment and longitudinal cfDNA samples for patients with RAS/BRAF mutant tumors." (PMID 39433569, 2024). "Specifically, BRAF inhibitors can promote the infiltration of immune cells within the tumor, such as CD8+ T cells and natural killer cells, which are crucial for recognizing and killing tumor cells." (PMID 39529955, 2024). "The optimized BRAF duplication screening assay was successfully multiplexed with different patient-specific targeted assays, enabling simultaneous assessment of tumor DNA fraction and BRAF CNV in patient samples." (PMID 38371226, 2024). "As for the other MKIs and selective kinase inhibitors, especially selective kinase inhibitors that restore RAI uptake in tumor cells (such as BRAF, MEK and mTOR inhibitors), encouraging results are shown in multiple clinical trials." (PMID 39473507, 2024). "This question has been raised by the CAIRO 5 trial, in which initial unresectable CRC with hepatic metastases have been treated based on tumor sidedness and RAS/BRAF mutational status." (PMID 39682117, 2024). "For a given specimen, pathogenic variants of BRAF, EGFR, KRAS, and NRAS were identified and the determined VAFs were correlated with the corresponding tissue tumor cellularity." (PMID 38397405, 2024). "Tumor recurrence or regrowth was observed in seven patients at a significantly higher rate for FGFR1 mutations (50.0%, 4/8) than BRAF V600E mutations (6.3%, 2/32; p = 0.048)." (PMID 39081340, 2024). "According to ASCO guidelines, patients with EC should undergo comprehensive biomarker assessments, including HER2, PD‐L1, dMMR/MSI‐H, NTRK, BRAF, RET, and tumor mutational burden (TMB) testing." (PMID 39415846, 2024). "Further analysis of the impact of the BRAF status of mCRC, through later lines of therapy and by tumour sidedness, is warranted." (PMID 38402342, 2024). "This has important implications for our understanding of how this BRAF inhibitor impacts tumor growth and provides novel therapeutic target and combination possibilities." (PMID 38421883, 2024). "In conclusion, systemic anti-tumor therapy with ICI or BRAF/MEKi induces an increased expression and release of pro-coagulant factors." (PMID 39487855, 2024). "Although BRAF inhibitors suppress tumor growth by inhibiting the MAPK pathway, their effectiveness is limited due to pathway reactivation." (PMID 39519055, 2024). "Because the tumor findings, PDC NGS analysis, and PDC drug sensitivity test suggested both ALK-positive cells and BRAF-mutated malignant cells, the combined effect of an ALK-TKI and a BRAF inhibitor was tested on the PDC." (PMID 38398169, 2024). "During ICI treatment in PR patients, BRAF and APC mutations shifted as the tumor responded to or resisted treatment." (PMID 39796090, 2024). "Tumor responses were demonstrated across the three response assessment criteria (RANO-HGG, RAPNO and RANO-LGG), BRAF alteration type (mutation versus fusion) and prior MAPKi use, including patients who progressed on a MAPKi as their most recent prior therapy." (PMID 37978284, 2024). "Two BRAF-mutant PDAC patients showed a significant reduction in carbohydrate antigen 19-9 levels, a PDAC-associated tumor antigen, following co-treatment with dabrafenib plus trametinib." (PMID 38338909, 2024).